TERT (telomerase reverse transcriptase)
Diseases named in the same sentence as TERT in open-access papers (continued):
Sharing a sentence is not in itself a finding about the gene and the disease.
metastatic melanoma (16 papers, 2014 to 2025). A melanoma that has spread from its primary site to another anatomic site. "TERT promoter mutations have been discussed as potential prognostic factors in metastatic melanoma and as potentially predictive most recently under BRAF/MEK and anti-CTLA4 therapy." (PMID 37418389, 2023). "The increased frequency of TERT promoter mutations in metastatic melanoma is associated with higher invasiveness." (PMID 35903534, 2022). "Almost every metastatic melanoma in our cohort harbored one of three cancer-associated TERT aberrations (promoter point mutation, structural rearrangement, or methylation)." (PMID 36011010, 2022). "recently identified an association between a higher TMB and TERT mutations, conferring an improved prognosis in patients with metastatic melanoma receiving CTLA-4 blockade, and thus, for combined targeting of telomerase and CTLA-4 in these patients." (PMID 34046035, 2021). "According to other studies, up to 85% of TERT promoter mutations have been found in metastatic melanoma, while 30–40% of TERT promoter mutations have been found in primary melanoma." (PMID 32894090, 2020). "Tumor tissue samples from 22 stage IV (AJCC) metastatic melanoma patients were tested for C228T and C250T TERT promoter mutations by ddPCR using the TERT assay." (PMID 29108273, 2017). "In this study, we cataloged TERT genetic alterations (promoter mutations or structural rearrangements), allele-specific promoter methylation patterns, and allele-specific expression levels in 70 metastatic melanomas and 54 cancer cell lines." (PMID 36011010, 2022). "In addition, plasma samples from 56 metastatic melanoma patients and 56 healthy controls were tested for TERT promoter mutations." (PMID 29108273, 2017). "Given that some metastatic melanomas harbored both mutated and methylated TERT distal promoters, we next asked whether mutation and methylation tended to occur on the same promoter molecule (i.e., in cis on the same allele) or on separate molecules (i.e., in trans on homologous alleles)." (PMID 36011010, 2022). "The only other log2 fold-change greater than 1 is seen in the ICGC cohort for TERT expression (increase in metastatic melanoma)." (PMID 38030698, 2023). "The TERT ddPCR assay detected a statistically significant difference in the copies of mutant TERT ctDNA in plasma from metastatic melanoma patients relative to those from healthy controls (p=0.006)." (PMID 29108273, 2017). "We tested the entire cohort of 17 metastatic melanoma patients for C228T and C250T TERT promoter (pTERT) mutations by ddPCR, as this region was not covered by the NGS panel." (PMID 38548846, 2024). "Therefore we investigated the impact of both TERT alterations using univariate and multivariate survival analyses based on six bulk RNA-seq cohorts of metastatic melanoma treated with ICI (Gide, Riaz, Van Allen, Liu, Hugo cohorts) and without targeted therapy or ICI (SKCM)." (PMID 37418389, 2023). "Our assay allowed for detection of mutant TERT in biologically relevant samples, such as FFPE tumor DNA and plasma of metastatic melanoma patients at high specificity." (PMID 29108273, 2017). "In contrast to the correlative association between MITF and c-MYC in single-cell RNA-seq data sets on metastatic melanoma, preliminary data indicate that expression of c-MYC appears to be decoupled from MITF at the protein level in bulk MITF-low tumor cells and TERT-immortalized melanocytes." (PMID 30651597, 2019). "As expected, the ALT-positive metastatic melanoma (sample #6) did not express TERT." (PMID 36011010, 2022).
squamous cell carcinoma (16 papers, 2012 to 2025). A carcinoma arising from squamous epithelial cells. "We investigated the presence of TERT promoter mutations in 32 basal cell carcinomas and 34 cutaneous squamous cell carcinomas using conventional Sanger sequencing." (PMID 24260374, 2013). "Indeed, TERT promoter mutations are frequently detected in tumours of the oral cavity (47%) and larynx/hypopharynx (12%), while they are rare in squamous cell carcinoma of the oropharynx (1%)." (PMID 38033865, 2023). "The frequency of TERT promoter mutations in intraepithelial neoplasia grade 1-3 (CIN1-3) and squamous cell carcinoma of the conjunctiva was significantly higher in HIV-positive (between 32% and 46%) compared to HIV-negative patients (between 13% and 22%)." (PMID 38033865, 2023). "Among direct Notch target genes are multiple DNA damage response genes, including IER5, which we show is required for Notch-induced differentiation of squamous carcinoma cells and TERT-immortalized keratinocytes." (PMID 32936072, 2020). "Notably, TERT mRNA expression levels were much higher in SiHa cells than in squamous cell carcinoma-derived CaSki and C-4I cells, as well as adenocarcinoma-derived HeLa cells, despite comparable expression levels of HPV E6." (PMID 38033865, 2023). "Our study shows that TERT promoter mutations with UV-signatures are frequent in non-melanoma skin cancer, being present in around 50% of basal and squamous cell carcinomas and suggests that increased expression of telomerase plays an important role in the pathogenesis of these tumors." (PMID 24260374, 2013). "Gains in chromosome 3q26 commonly represent chromosomal instability in squamous cell cancers and adenocarcinomas, independent of specific TERT overexpression, and are found in a high proportion of head and neck, lung, esophageal, colon, pancreatic, breast, cervix and vulvar cancers." (PMID 22792164, 2012).
Alpha-thalassemia (15 papers, 2017 to 2025). Alpha-thalassemia is an inherited hemoglobinopathy characterized by impaired synthesis of alpha-globin chains leading to a variable clinical picture depending on the number of affected alleles. "The mutations in epigenetic modifiers, such as isocitrate dehydrogenase (IDH1/2), telomerase reverse transcriptase (TERT), and alpha-thalassemia/mental retardation syndrome X-linked (ATRX), which lead to global changes in the epigenome, are common drivers of gliomagenesis." (PMID 28698530, 2017). "The stemness index was significantly lower in alpha-thalassemia/mental retardation, X-linked (ATRX) mutant samples than in wild-type samples but significantly higher in the telomerase reverse transcriptase (TERT) mutant group." (PMID 38229597, 2024). "In one case without TERT-promoter mutation an alpha thalassemia/mental retardation syndrome, X-linked (ATRX)-frameshift insertion was detected." (PMID 33876327, 2021). "Also, molecular classifiers of outcome include loss of heterozygosity (LOH) of 1p19q, telomerase reverse transcriptase (TERT), alpha-thalassemia/mental retardation syndrome X-linked (ATRX), or isocitrate dehydrogenase (IDH)-1 or -2 mutations." (PMID 30463322, 2018).
colon cancer (15 papers, 2015 to 2025). "Immunohistochemical results showed that compared with normal colon tissues, MSI2, EZH2, and NCL were significantly higher expressed in colon cancer tissues except TERT." (PMID 40535805, 2025). "Wu also found that XAV939 reduces the CSC markers (EpCAM, TERT) and increases chemosensitivity in colon cancer cells by inhibiting the Wnt signaling pathway." (PMID 35717205, 2022). "The reason for the lower survival rate of group 2 of colon cancer samples with respect to CCNB1_TERT can be explained by the expression pattern of TERT." (PMID 31856825, 2019). "But TERT promoter hypermethylation is more prevalent (>70%) in cancer types without TERT mutation (e.g., lung, breast, prostate, and colon cancers), implying that epigenetic mechanisms are the drivers of upregulation of TERT expression in these cancer types." (PMID 37575241, 2023). "Cytotoxic T lymphocytes that are reactive to TERT and VEGFR-2 are capable of mounting an anti-tumour response in murine breast and colon tumour models and in a lung metastatic model." (PMID 26085010, 2015). "In their 2015 study using HCT116 and SW480 colon cancer cell lines, the Yang lab found that by physically interacting with the transcriptional repressor zinc finger E box-binding homeobox 1 (ZEB1), TERT downregulates the expression of E-cadherin, a tumor suppressor whose loss-of-function drives EMT." (PMID 32599885, 2020). "In addition, in another public transcript data set (GSE76342) for the colon cancer cell line LoVo with or without metformin treatment, we found that metformin inhibited expression of the CSC markers Lgr5, ASCL2, EPHB3, OLFM4, BMI1, Lrig1, TERT, CD44, and CD133." (PMID 32911743, 2020).
esophageal cancer (15 papers, 2014 to 2026). A primary or metastatic malignant neoplasm involving the esophagus. "In this study, we conducted an extensive association analysis to evaluate the roles of TERT gene polymorphisms and haplotypes on susceptibility to esophageal cancer in a population of northwestern Chinese patients from a single case-control study." (PMID 28060765, 2017). "Next, we examined the association between TERT SNPs and esophageal cancer risk using genetic models; p-values were calculated using the Wald test." (PMID 28060765, 2017). "In conclusion, we demonstrated that the rs10069690, rs2242652, and rs2853676 genetic polymorphisms in the TERT loci are associated with an increased risk of esophageal cancer in a northwestern Chinese patient population." (PMID 28060765, 2017). "In this study, we analyzed the association between TERT SNPs and risk of esophageal cancer in 386 esophageal cancer patients and 495 healthy subjects from the Xi’an area of China." (PMID 28060765, 2017). "We found that the rs10069690, rs2242652, and rs2853676 TERT genetic polymorphisms were associated with an increased risk of esophageal cancer in a northwestern Chinese patient population." (PMID 28060765, 2017). "In the present study, we systematically examined the impact of four SNPs in the TERT loci on susceptibility to esophageal cancer." (PMID 28060765, 2017). "In all cases in which a TERT variant was identified in esophageal cancer, the same variant was detected in matched normal esophageal mucosa." (PMID 24983628, 2014). "Single nucleotide polymorphisms (SNPs) in TERT may be associated with susceptibility to esophageal cancer and contribute to the development of esophageal cancer." (PMID 32068233, 2020). "Single nucleotide polymorphisms (SNPs) in TERT may be associated with susceptibility to esophageal cancer." (PMID 28060765, 2017). "Finally, a haplotype-based association study was performed to examine associations between TERT haplotype and risk of esophageal cancer, and p-values were calculated using the Wald test." (PMID 28060765, 2017). "Functional data in esophageal cancer cells overexpressing TERT A279T induced telomere dysfunction but interestingly decreased proliferation of these cells." (PMID 31470906, 2019). "Four SNPs in the TERT gene were genotyped in the esophageal cancer patients and the healthy controls." (PMID 28060765, 2017). "Several studies have shown that TERT promotes tumor invasion and metastasis in gastric, liver, and esophageal cancer." (PMID 28060765, 2017). "After measuring TERT and CLPTM1L expression in sixty-six pairs of esophageal cancer and normal tissues, we observed that the rs2736100 G risk allele carriers showed elevated oncogene TERT expression." (PMID 26716642, 2016). "Subsequent immunohistochemistry experiments demonstrated that β-galactosidase levels were significantly higher in A279T-transduced esophageal cancer cells relative to respective TERT-transduced or vector control cells." (PMID 24983628, 2014). "Sequencing techniques were used to evaluate mutational status of telomerase reverse transcriptase (TERT) and telomerase RNA component (TERC) in neoplastic and adjacent normal mucosa from 143 esophageal cancer (EsC) patients." (PMID 24983628, 2014). "For instance, we observed that β-catenin was markedly depleted in cancer cells expressing A279T, and that A279T attenuated TERT-mediated chemoresistance in esophageal cancer cells." (PMID 24983628, 2014). "Interestingly, the expression of SNAIL1 and TERT directly correlated with the expression of miR‐196a in the TCGA cohort of 109 patients with esophageal cancer." (PMID 40955778, 2025). "The threonine substitution at this amino acid in TERT negatively influences telomere length and proliferation in esophageal cancer cell lines compared with alanine, and leads to reduced Wnt signaling through destabilization of complexes containing TERT, transcription activator BRG-1 and β-catenin." (PMID 27579533, 2016).
esophageal cancer (continued). "As such, additional studies were undertaken to ascertain if the TERT A279T variant affected non-canonical TERT activity in esophageal cancer cells." (PMID 24983628, 2014).
brain cancer (14 papers, 2010 to 2025). A primary or metastatic malignant neoplasm affecting the brain. "Molecular mechanisms converging on TERT up-regulation were recently reported to be associated with dismal prognosis in pediatric brain cancers." (PMID 24174164, 2013). "Variants in the TERT-CLPTM1L locus have been identified by GWAS to harbor susceptibility alleles for cancer of the brain, pancreas and lung." (PMID 20700438, 2010). "Mutation of the promoter of TERT, which encodes a telomerase, would lead to an uncontrolled proliferation of tumor cell and is believed to be a precondition for the formation of brain cancer; this could lead to higher FA and lower MD values, as we observed." (PMID 33777772, 2021). "Reporter assays in cervix and brain cancer cell lines revealed a significant drop in TERT expression, when this upstream region was unmethylated." (PMID 37993930, 2023). "In some solid cancers like HCC and brain cancer, high DNA methylation of THOR has been associated with TERT expression." (PMID 37993930, 2023). "Genotypes of MNS16A, a functional polymorphic tandem repeat minisatellite of TERT locus, have been investigated in cancers of the brain, breast, lung, colorectum, nasopharynx, prostate, blood, and kidney." (PMID 28427205, 2017). "Some of the important DNA aberrations such as 1p/19q co-deletion and TERT promoter mutation useful as diagnostic, prognostic and predictive brain cancer biomarkers have not been studied in exosomes." (PMID 33137926, 2020). "Several studies have shown that increased levels of a specific mutation in the blood can be found significantly earlier than a radiologic or clinical progression and IDH R132H mutation, TERT promotor mutation, and MGMT promotor methylation has been detected in brain cancer." (PMID 31320993, 2019). "Interestingly, whereas the plasma mutational panel interrogates the TERT promoter region, only one of 49 samples was positive for a TERT mutation not previously reported in patients with brain cancers." (PMID 40299319, 2025). "More accuracy on TMMs of paediatric brain cancer can be obtained by careful analysis of pathological specimens, including the combined staining for ALT-associated PML bodies (APB) and TERT, but these approaches are still not enough as stainings are variable and their diagnostic value is unclear." (PMID 32331249, 2020).
breast tumors (14 papers, 2004 to 2025). "Consistently, in breast tumors and cell lines, the CC genotype also tends to be associated with an elevated expression of TERT (p = 0.102 in tumors and cell lines), which we and others have found to also be associated with a poor prognosis." (PMID 36768147, 2023). "In breast tumors, TERT overexpression was associated with tumor aggressiveness and poor survival after adjuvant and neoadjuvant chemotherapy." (PMID 29100407, 2017). "Interestingly, the CC genotype was also associated with a 1.6-fold higher TERT expression than CT + TT in breast tumors (see Section 2.4)." (PMID 36768147, 2023). "It is also noteworthy that the expression of the TERT gene, encoding telomerase reverse transcriptase, was significantly upregulated in DNA aneuploid breast tumors compared to DNA diploid breast tumors, confirming that aneuploidy may also be caused by telomere erosion." (PMID 21352579, 2011). "We conclude that transduction of normal HMECs with lentiviruses expressing ERα, BMI1, MYC and TERT confers the ability to form metastatic ERα-positive breast tumours." (PMID 17573968, 2007). "Sequencing analysis of a cohort of fibroepithelial breast tumors revealed that the frequency of TERT alterations increased from benign (18%) to borderline (57%) and malignant phyllodes tumors (68%; p < 0.01), with TERT alterations being associated with higher levels of TERT mRNA (p < 0.001)." (PMID 39996866, 2025). "We found TERT copy number gains in more than 20% of primary breast tumors examined." (PMID 29100407, 2017). "We previously showed that when SFRP1 is knocked down in immortalized non-malignant mammary epithelial cells, the cells (TERT-siSFRP1) acquire characteristics associated with breast tumor initiating cells." (PMID 21303533, 2011). "Pairwise analysis of primary breast tumors with matched central nervous system (CNS) metastases uncovered striking patterns of SLX4IP and TERT expression." (PMID 32071280, 2020). "MKI67 and TERT were significantly upregulated in the 23 DNA aneuploid breast tumors, while ESR1/ERα expression was similar in the diploid and aneuploid breast tumor subgroups." (PMID 21352579, 2011). "Two largely non-overlapping groups were observed among the 106 breast tumors analyzed, one with moderate TERT overexpression (up to ≈25-fold compared to controls; 46%) and the other with high-level overexpression (≈32- to 810-fold; 54%)." (PMID 36768147, 2023). "We detected no activating TERT promoter mutations, including hotspot mutations C228T and C250T, in 77 pre-NCT breast tumor biopsies (cohort #1) and 45 post-NCT residual tumors (cohort #2)." (PMID 29100407, 2017). "We demonstrate in this study that the levels of TRF2, TRF1, TIN2, and POT1 mRNA, but not TERT mRNA, are inversely correlated with telomere content (a surrogate for telomere length) in human breast tumor tissues." (PMID 23342266, 2012). "The levels of TRF2, TRF1, TIN2, and POT1 mRNA, but not telomerase reverse transcriptase (TERT) RNA, are inversely correlated with telomere content in breast tumors." (PMID 23342266, 2012). "Telomere content assays and quantitative RT-PCR demonstrate that the levels of TRF2, TRF1, TIN2, and POT1 mRNA, but not telomerase reverse transcriptase (TERT) RNA, are inversely correlated with telomere content in breast tumors." (PMID 23342266, 2012).